MIR548AE1 (microRNA 548ae-1)
Synonyms: hsa-mir-548ae-1
Gene: MicroRNA gene on chromosome 2 (184,378,975 to 184,379,044, forward strand). Ensembl gene ENSG00000266808.
Homologues: Orthologues: chimpanzee MIR548AE1 (100% identical). Paralogues in human: MIR548S (67% identical), MIR548AH (63% identical), MIR548AJ1 (63% identical), MIR548H3 (61% identical), MIR548O2 (61% identical), MIR548X (61% identical), MIR548AZ (60% identical), MIR548P (60% identical), MIR548X2 (60% identical), MIR548AA1 (59% identical), MIR548AN (59% identical), MIR548F3 (59% identical), and 13 more.